MC4R (melanocortin 4 receptor)
Diseases named in the same sentence as MC4R in open-access papers (continued):
Sharing a sentence is not in itself a finding about the gene and the disease.
Obesity (continued). "Moreover, the genetic aspect of obesity, particularly the role of specific polymorphisms in genes like obesity-associated (FTO), leptin (LEP), leptin receptor (LEPR), and melanocortin 4 receptor (MC4R) genes, has been extensively studied." (PMID 38398881, 2024). "However, unlike what is observed with loss of MC4R, obesity in mBrGsKO mice is not driven by hyperphagia, and the anorectic effects of a melanocortin agonist remain intact." (PMID 38175730, 2024). "Importantly, due to the involvement of PHIP in the leptin-melanocortin pathway, affected individuals with CHUJANS who suffer from therapy resistant obesity can participate in a clinical trial with an anti-obesity drug (setmelanotide (MC4R-agonist), ClinicalTrials.gov identifier: NCT04963231)." (PMID 38787418, 2024). "Most interestingly, there are notable differences in weight as a function of MC4R haploinsufficiency at approximately 60 days of age and as a function of the obesogenic diet at approximately 120 days of age, consistent with the development of adult-onset obesity." (PMID 39741559, 2024). "Furthermore, recent studies highlight that extended inhibition of projections from melanocortin-4 receptor-expressing neurons in the paraventricular hypothalamus to the LS may precipitate obesity due to reduced energy expenditure." (PMID 38948475, 2024). "Additionally, supplementation of L. rhamnosus GG (LGG) and B. lactis to pregnant women has been shown to decrease the DNA methylation of the fat mass and obesity associated gene (FTO) and melanocortin-4 receptor gene (MC4R) in both women and their infants (p < 0.05)." (PMID 39000282, 2024). "The lack of a significant association in males (p > 0.05) suggests that the MC4R rs17782313 SNP may not be a major determinant of obesity risk in men within our study population." (PMID 38002939, 2023). "Setmelanotide, an MC4R agonist that activates MC4R pathway signaling, is an approved treatment option in the United States and European Union for chronic weight management and control of hunger in adult and pediatric patients aged 6 years and older with syndromic obesity due to BBS." (PMID 37415189, 2023). "Mc4r-KO mice may recapitulate the liver pathology of human obesity-related metabolic disorders." (PMID 37681411, 2023). "Furthermore, as the causal factors of genetic variants vary across populations, our findings shed light on the Israeli population, which, to the best of our knowledge, was not investigated regarding the effect of MC4R rs17782313 and on obesity risk." (PMID 38002939, 2023). "To clarify the effects of hepatic FASN deficiency on NAFLD and diabetes in obese mice in the setting of NCD overfeeding without leptin deficiency, we next studied Mc4r-KO mice as an alternative mouse model of hyperphagic obesity associated with hepatic FASN upregulation and hyperleptinemia." (PMID 37681411, 2023). "Thus, the failure of efforts to generate an effective treatment based on the MC4R action against obesity may largely stem from the inability of MC4R action on reducing weight rather than the effect on MC4R activation." (PMID 37069175, 2023). "MC4R variants that do not completely disrupt protein function may lead to influence the individual’s polygenic susceptibility to obesity." (PMID 38002939, 2023). "The most prominent and ubiquitous characteristic of children identified with biallelic (likely) pathogenic variants in LEP, LEPR, and MC4R genes was the onset of severe obesity and hyperphagia at a very young age—they lacked satiety and were constantly in demand of food." (PMID 37659411, 2023). "Notably, his sister with a BMI of 74.31 kg/m2 was diagnosed with MC4R-obesity as well." (PMID 37327085, 2023). "Monogenic obesity is caused by variants of only one gene, and several genes have been associated with this type of obesity, such as leptin (LEP), leptin receptor (LEPR), pro-opiomelanocortin (POMC), and melanocortin 4 receptor gene (MC4R), which is the most common form of monogenic obesity." (PMID 38003013, 2023).
Obesity (continued). "Therefore, it seems necessary to compare the results obtained with other potential indicators in the future, like molecular indicators including variants of different risk alleles to determine polygenic or common obesity, including FTO, TNF-α, MC4R, ENPP1 genes, etc.." (PMID 37761477, 2023). "This shows that the MC4R gene could control both energy intake and energy expenditure, supporting the evidence that, in rodents, MC4R contributes to mediating energy homeostasis, food intake, and obesity." (PMID 35538513, 2022). "Therefore, MC4R has been considered as a potential target for obesity treatment." (PMID 35818295, 2022). "Mc4r−/− mice consuming an HFD (60% energy as fat) for 20 weeks develop hepatic microvesicular and macrovesicular steatosis, ballooning degeneration, inflammation and pericellular fibrosis, a phenotype compatible with NASH, associated with obesity, insulin resistance, and dyslipidemia." (PMID 36555433, 2022). "Several syndromic and monogenic disorders of obesity that have been identified include Prader–Willi syndrome, Bardet–Biedl syndrome, and loss-of-function mutations in the genes encoding for pro-opiomelanocortin (POMC), leptin, leptin receptor (LEPR) or the melanocortin-4 receptor (MC4R)." (PMID 35299971, 2022). "Therefore, MC4R has become a promising GPCR drug target for severe obesity therapy." (PMID 35741395, 2022). "Consequently, pleiotropic genes like LEPR and MC4R could influence the phenotype of both obesity and precocious puberty; however, their effect on precocity puberty and its magnitude are still unknown." (PMID 35624438, 2022). "In addition, different studies demonstrated the anti-obesity effect of celastrol was independent on melanocortin 4 receptor (MC4R), and lipocalin 2 (Lcn2), because the deletion of these genes did not weaken the weight-loss and liver-protecting effect of celastrol in mice." (PMID 35444532, 2022). "Genes encoding leptin (LEP), leptin receptor (LEPR), melanocortin 4 receptor (MC4R), proprotein convertase subtilisin/kexin type 1 (PCSK1), proopiomelanocortin (POMC), kinase suppressor of ras 2 (KSR2), adenylate cyclase 3 (ADCY3), and others contribute to the development and progression of obesity." (PMID 36141228, 2022). "There is currently no standardized protocol for obesity treatment in patients with MC4R mutations." (PMID 36553534, 2022). "Finally, our structures reveal mechanistic details of MC4R activation/inhibition, and provide important insights into the regulation of the receptor signaling profile which will facilitate the development of tailored anti-obesity drugs." (PMID 34561620, 2021). "Hence, BS is often considered as the obesity treatment of choice for individuals with MC4R-d." (PMID 35095762, 2021). "Currently described non-syndromic forms of mendelian obesity comprise mainly genetic defects in the leptin/melanocortin pathway, such as mutations in the genes encoding LEP, LEPR, prohormone convertase 1 (PC1/3), proopiomelanocortin (POMC) and melanocortin receptor 4 (MC4R), leading to overeating." (PMID 33800718, 2021). "Oral (per os) administration of this PC promoted the restoration of the anorexic effect of the MC4R agonist, melanotan II (MTII), in mice harboring the obesity-causing mutant form R165W-hMC4R but not in the loxP-flanked transcriptional blocking (loxTB) MC4R-null mice." (PMID 33434184, 2021). "Using a NanoBiT protein:protein interaction assay, we found that obesity-associated mutants that did not affect cell surface expression in the basal state frequently impaired the interaction between MC4R and β-arrestin-1, β-arrestin-2, or more frequently both β-arrestins." (PMID 33761344, 2021). "It therefore remains unclear whether carriers of MC4R mutations respond differently to a structured longitudinal lifestyle intervention targeting obesity when compared to noncarriers." (PMID 32921795, 2021).
Obesity (continued). "While the prevalence of carriers of MC4R mutations varies with ethnicity, up to 2% carry damaging mutations in MC4R among samples of non-consanguineous individuals with obesity of European descent, making MC4R deficiency the most common form of monogenic obesity." (PMID 32921795, 2021). "We show that many of the MC4R mutations previously reported to cause severe early onset obesity may not be as pathogenic as previously thought." (PMID 32692746, 2020). "Furthermore, it is not clear why some carriers of MC4R mutations maintain a normal weight, even when the mutation was shown to increase risk of obesity." (PMID 32692746, 2020). "Most interestingly, we show that some carriers seem able to counteract the obesity-increasing effects of the MC4R mutations they carried and remain of normal weight because—at least in part—of their substantially lower polygenic susceptibility (>1 SD in PRSBMI) than carriers with obesity." (PMID 32692746, 2020). "Variants residing in the gene SIM1 have also been associated with severe obesity and Prader–Willi-like syndromes, an effect attributed to this transcription factor’s integral role in development of the PVN, a hypothalamic nucleus, which is most notable as the major site of MC4R expression." (PMID 33233816, 2020). "Thus, the lack of POMC binding at MC4R or mutations in propeptide convertases 1 can lead to early-onset of obesity." (PMID 32272767, 2020). "Risk of obesity among MC4R carriers and noncarriers with high and low polygenic risk." (PMID 32692746, 2020). "However, carriers with obesity had a higher BMI (likely because of more lean mass) than noncarriers with obesity, consistent with was has been observed for MC4R mutations carriers before." (PMID 32692746, 2020). "In this regard, we previously reported that genetically obese melanocortin 4 receptor–deficient (MC4R-KO) mice fed Western diet (WD) can act as a novel murine model that sequentially develops hepatic steatosis, NASH, and HCC in the presence of obesity and insulin resistance." (PMID 31969650, 2020). "Our study showed that several risk variants for obesity or metabolic diseases (FTO rs1121980, KCNQ1 rs163182, MC4R rs12970134, and PROX1 rs340841) were also associated with GDM, giving further evidence that GDM and obesity/metabolic diseases may share a similar genetic background." (PMID 32390949, 2020). "Notably, other loci such as MC4R, PCSK1, and BDNF, are well known to be associated with severe early-onset obesity and harbor genes involved in the regulation of leptin-melanocortin pathways in the hypothalamus, thus are thought to affect body weight largely through impacting appetite." (PMID 31285522, 2019). "However, the association between the genetic variations of the MC4R gene and obesity with different metabolic abnormalities is still not fully elucidated." (PMID 31781208, 2019). "However, this and other studies have not detected significant associations for other MC4R LoF variants with obesity in the general population." (PMID 31002796, 2019). "Also, MC4R gene involves in the key metabolic processes such as regulation of food consumption and energy balance; and the abnormalities in this gene can lead to decrease in satiety and onset of obesity." (PMID 32010189, 2019). "Thus genetic screening of consanguineous families with severe early-onset obesity, constitutes a powerful method of identifying causal homozygous mutations and has enabled the identification of rare damaging variants in e.g. LEP, LEPR and MC4R." (PMID 31488071, 2019). "Consequently, genetic testing should be advocated in children with early onset severe obesity as they may be suitable candidates for current or promising new drugs such as MC4R agonists." (PMID 30991789, 2019).
Obesity (continued). "Rare and pathogenic variations in the MC4R (MIM:155541), POMC (MIM:176830), LEP (MIM:164160), LEPR (MIM:601007) and few other genes of LEP‐melanocortin pathway have been found and very less frequency of mutations was accounted in different studies due to complexity in the pathogenesis of obesity." (PMID 31070016, 2019). "An even stronger decrease in cardiac UCP3 content was observed in the LoxTB MC4R−/− mice (28–34% decrease) and LepR/Nestin-cre mice (38–40% decrease), two other models of type 2 diabetes which are also characterized by severe obesity, insulin resistance, hyperinsulinemia, and glucose intolerance." (PMID 30374710, 2018). "Studies on the FTO rs9939609, the MC4R rs17782313, and the PPAR-γ rs1801282 polymorphisms conducted so far, focused mainly on searching for the relationships between these gene variants and symptoms of metabolic disorders (obesity, insulin resistance, hypertension, and hyperlipidemia)." (PMID 30271660, 2018). "This review will concentrate on the original obesity gene, leptin (LEP) and its receptor (LEPR), together with a gene that has been identified as having variants of strong effect giving rise to both monogenic obesity and obesity in the general population, the melanocortin-4 receptor (MC4R)." (PMID 30121879, 2018). "Interestingly, MC4R Ille251Leu (rs52820871) is reported in the literature as ameliorating obesity." (PMID 30121879, 2018). "Therefore, MC4R haploinsufficiency leads to obesity in mice." (PMID 29991773, 2018). "Among the six leptin-associated loci, three genes (MC4R, BDNF, and PCSK1) are known to be involved in the hypothalamic leptin–melanocortin pathway, thus it is not surprising that those three loci are found to be associated with obesity-related traits and leptin levels in our pediatric setting." (PMID 29212175, 2017). "Also, León-Mimila and colleagues revealed that the melanocortin 4 receptor variant (rs17782313) was associated with morbid obesity but not with class I/II obesity in a Mexican population." (PMID 29317790, 2017). "When further adjusted for BMI, the obesity predisposing loci, GNPDA2-rs16858082 (P = 0.016) and PCSK1-rs261967 (P = 0.026) were still nominally associated with total cholesterol (TC) levels, and MC4R-rs2331841 remained correlated with fasting glucose (FBG) levels (P = 0.012)." (PMID 29212175, 2017). "The association of MC4R SNPs with polygenic obesity will also not be further discussed here." (PMID 28615046, 2017). "Indeed, our findings suggest a potential effect of MC4R on glucose homeostasis beyond obesity." (PMID 29212175, 2017). "Indeed, current Genome Wide Association Studies (GWAS) point to several key genes with very important influences on the origin and development of obesity: these include Fat-Associated Obesity (FTO), Leptin, Leptin Receptor, Pro-Opiomelanocortin (Pomc), or Melanocortin Receptor 4 (Mc4r)." (PMID 28930194, 2017). "Several previous studies explored whether MC4R and lifestyle factors interacted on obesity." (PMID 28081251, 2017). "In addition, a MC4R selective drug is still an attractive anti-obesity target." (PMID 27467141, 2016). "There are no published reports of the impact of heterozygous MC4R mutations on hepatic steatosis in monogenic obesity, while polymorphisms in MC4R have been associated with alanine aminotransferase and BMI, but not with hepatic fat content in population-wide studies." (PMID 27899914, 2016). "On the other hand, results from a Danish study using the polymorphisms of the FTO and MC4R genes, and from a collaborative Canadian study using the FTO gene polymorphism as instruments for obesity, suggested a possible protective effect of obesity on psychological distress and depression." (PMID 26167892, 2015). "Furthermore, MC4R-agonism enhances peripheral insulin sensitivity and improves glucose tolerance in rodents and non-human primates, implying that MC4R-based drug therapies hold promise for treatment of type 2 diabetes and obesity." (PMID 25652173, 2015).
Obesity (continued). "Since unbalanced production of pro- and anti-inflammatory adipocytokines in obesity has been implicated in the pathogenesis of NASH, we examined serum adipocytokine concentrations and found that EPA treatment significantly increased serum adiponectin concentrations in MC4R-KO mice." (PMID 25816330, 2015). "While there may be a common unifying mechanism for all the obesity associated MC4R variants, none has been reported to date." (PMID 24705671, 2014). "Although none of the common variants achieved genome-wide significance (p < 7.2 × 10−8, Dudbridge and Gusnanto 2008), the role of MC4R in the development of obesity is well established, thus applying such stringent criteria for statistical significance in this study may be overly conservative." (PMID 25103139, 2014). "We now investigate whether common non-coding variation near MC4R also contributes to obesity." (PMID 25103139, 2014). "Furthermore, the reduction in TSPO expression was not a direct result of the exposure to high-fat diet per se because we were able to detect a decrease in TSPO levels in mitochondrial extracts from WAT and BAT from the MC4R−/− monogenic mouse model of obesity which were maintained standard chow." (PMID 24260329, 2013). "Interestingly, FTO, MC4R and BDNF loci were most significantly associated with class III obesity." (PMID 23950976, 2013). "In 1443 patients with a minor allele frequency (MAF) of 0.27, the variant rs17782313 located downstream the MC4R gene, presumably associated with increased obesity risk, was not shown to be related to maximal weight loss nor weight regain after bariatric surgery." (PMID 23185251, 2012). "POMC deficiency could also lead to obesity (due to lack of binding at MC4R), hypocortisolism (due to the lack of binding of ACTH to the MC2R in the adrenal gland), and alteration of pigment (due to lack of binding at MC1R in the skin)." (PMID 22474595, 2012). "Thus, MC4R antagonists may be useful to treat cachexia while MC4R agonists are being developed to treat obesity." (PMID 22474595, 2012). "On the other hand, other studies indicated that a common variant genetic variation near MC4R gene (rs17782313), a direct candidate gene for food intake and obesity, does not seem to have a relevant effect on weight loss in adults after a lifestyle intervention." (PMID 21695122, 2011). "Other genes such as MC4R, leptin and leptin receptor, Ghrelin (GHRL), peroxisome proliferator-activated receptor gamma (PPARG), oxytocin receptor (OXTR), prohormone convertase-1 and proopiomelanocortin have been implicated in human obesity and will be discussed elsewhere in this journal issue." (PMID 22043167, 2011). "In the GWAS detecting the association of obesity with the 3′ MC4R-SNP, the respective finding could not be explained by the two non-synonymous polymorphisms (Val103Ile, Ile251Leu)." (PMID 21085626, 2010). "Thus, we demonstrate that the currently known major common variants related to obesity overlap to a substantial degree between children and adults confirming previous observations for FTO, MC4R, TMEM18, NEGR1 and extending this observation to SEC16B, BDNF and BCDIN3D;." (PMID 20421936, 2010). "Exploration of associations between genotypes and metabolic/obesity related variables in patients with PCOS revealed some evidence for an association of variants in FTO and TCF7L2, whereas no indication of association was observable for SNPs in INSIG2 and MC4R." (PMID 20092643, 2010). "In fact, studies showing mutations in the obese as well as in the normal weight individuals failed to establish that the early onset of obesity and the tall stature of the obese children are specific clinical characteristics of functionally relevant MC4R mutations." (PMID 19284607, 2009). "On the other hand, studies confuting the association between the MC4R mutations and early onset obesity describe populations of obese adults without objective data on whether the obese adults had been obese as children or not." (PMID 19284607, 2009).